CCK (cholecystokinin)
Diseases named in the same sentence as CCK in open-access papers (continued):
Sharing a sentence is not in itself a finding about the gene and the disease.
Obesity (continued). "Cholecystokinin antagonists are investigated to use against pancreas and hepatocarcinomas, the risks of which are higher in obesity with poorer prognosis than in nonobese patients." (PMID 40586867, 2025). "For obese patients with increased CCK levels, L. acidophilus H-68 is not the best choice for adjuvant obesity treatment." (PMID 38731751, 2024). "In states of obesity, the gram-positive bacterial production of lipoteichoic acid (LTA) or its gram-negative equivalent, LPS, induces local inflammation, diminishing NG sensitivity to leptin, but also to CCK, GLP-1, and PYY." (PMID 38613104, 2024). "Of particular interest, in the stress-induced obesity, HTR2A interacts with CCK and GHSR." (PMID 39062927, 2024). "Our findings suggest that the serum lipid-lowering treatments may alleviate obesity-induced AHR and lung fibrosis through anti-inflammatory responses by inhibition of RAS and NLRP3 inflammasome, and CCK activity." (PMID 38762465, 2024). "Further, these alterations in gut microbiota have been shown to promote important changes in satiation signals including gut hormones (leptin, ghrelin, GLP-1, peptide YY and CCK) and orexigenic and anorexigenic neuropeptides (AgRP, NPY, POMC, CART) that influence hyperphagia and therefore obesity." (PMID 37571301, 2023). "Unfortunately, few studies have assessed concentrations of CCK in individuals with and without obesity, and we were therefore unable to run a meta‐analysis on this hormone." (PMID 36416279, 2023). "Our results, however, do not identify which CCK source (circulating or ASM-secreted) contributes more greatly to obesity-induced AHR." (PMID 36599824, 2023). "This study explored the effect of three different modes of resistance training on appetite hormones [leptin, ghrelin, cholecystokinin (CCK), glucagon-like peptide-1 (GLP-1), and peptide tyrosine–tyrosine (PYY)], cardiometabolic and anthropometric measures in males with obesity." (PMID 35264977, 2022). "In light of such limitations, we did not further analyze other physiological obesity markers such as orexigenic peptides such as neuropeptide Y, ghrelin, CCK, or orexin in the present study." (PMID 36612600, 2022). "Whether obesity and TD2M affect CCK secretion is controversial because of the lack of a good experimental model to study I cells secreting CCK." (PMID 35887100, 2022). "Although disrupted vagal signaling is not thought to primarily cause diet-induced obesity, several studies have shown diminished vagal sensitivity to key satiety hormones (i.e. GLP1 and CCK) in obesity." (PMID 34626852, 2021). "Thus, we cannot exclude that the absolute number of CCK-, PYY- and GIP-positive cells is enhanced in obesity." (PMID 33037328, 2021). "Studies in humans and animals have shown that administration of CCK, PYY, GLP-1, and NMB could decrease food intake but administration of ghrelin and NPY leads to obesity." (PMID 21390334, 2011). "CCK has long been known to suppress food intake and conversely, damage to the VMH [reviewed in 43] and LPB have been reported to lead to hyperphagia and obesity." (PMID 21085653, 2010). "A variety of CCK anti-obesity drugs in early clinical development have failed to progress in later clinical trials presumably in part because of a lack of efficacy beyond an initial reduction in hunger." (PMID 18307772, 2008). "Relative to those in the normal control group, the rats in the model group showed decreases in CCK and GLP-1 levels, and increases in leptin, ghrelin and orexin A levels, indicating that obesity could result in the imbalance in appetite-related gastrointestinal hormones." (PMID 40176906, 2025). "Furthermore, individuals with obesity have reduced fasting levels of PYY and GLP-1 and blunted meal-stimulated levels of these anorectic peptides, in addition to an attenuated satiety-promoting effect of CCK, leptin resistance, and IR." (PMID 35334929, 2022).
Obesity (continued). "CCK acts at the vagal afferent CCK1R to mediate postprandial satiety; however, while full agonist drugs of this receptor have stimulated weight reduction in patients, they have not achieved the primary end point of exceeding the effectiveness of acute dieting in clinical trials for obesity." (PMID 34950108, 2021). "Importantly, the PAM activity of Compound 1 was equivalent for CCK-58 that is the predominant circulating form of CCK, and for augmentation of CCK signaling at rat and monkey CCK1R that represent critical animal models for preclinical assessment of potential anti-obesity drug." (PMID 34950108, 2021). "We believe that this dysfunction of cholecystokinin stimulus-activity coupling could have had a negative impact on previous trials of CCK1R agonists in obesity." (PMID 34149622, 2021). "Recognition that CCK, acting through CCK1R, is one of the most prominent and earliest recognized physiologic regulators of appetite stimulated extensive pharmaceutical efforts to develop full agonists targeting this receptor as potential treatments for obesity." (PMID 34950108, 2021). "Furthermore, CCK in a stabilized form resistant to degradation in the GI tract is effective at reducing food intake and body weight in DIO rodents, and activating CCKA receptors enhances the anti-obesity properties of GLP-1 agonists, amylin, and leptin." (PMID 31281260, 2019). "Therefore, the satietyogenic effect presented by TTIp in this study can also be justified by the improvement of the sensitivity to CCK, regardless of its plasma increase, which is conditioned by the reduction of leptin, which is usually high in obesity." (PMID 30818882, 2019). "Furthermore, glucose reduction (via inhibition of the sodium-glucose like transporter 2) improved β cell function and suppressed islet CCK expression and tumor development in the KCO model, arguing that interventions that attenuate obesity-induced β cell stress may subvert tumorigenesis." (PMID 37648285, 2023). "Thus, the hypothesis that the action of TTI and pTTI are related to satiety in obesity is likely dependent on the action of these inhibitors on leptin and not on CCK, as seen for eutrophic animals." (PMID 29322840, 2018). "It is worth mentioning that the reduced sensitivity to CCK in obese animals is considered a factor for the continuity of this metabolic condition since even in physiological CCK doses administered to rats with obesity, there is no satietogenic effect as there is in eutrophic animals." (PMID 29322840, 2018). "For obesity treatment, this strategy may prove to be a more an effective strategy to reduce food intake than monohormone treatment, since the stimulation of GLP-1 secretion should lead to simultaneous release of the costored anorectic hormones CCK, glicentin, oxyntomodulin, and PYY, as reviewed." (PMID 24525020, 2014). "Even if no true differences in CCK (or GLP‐1) plasma concentrations exist between individuals with and without obesity, one cannot rule out the importance of the vagus nerve in regulating appetite." (PMID 36416279, 2023). "Some studies were also conducted in patients with obesity or metabolic syndrome, showing that acute administration of β-glucan enriched foods dose-dependently increases PYY, increases CCK without affecting ghrelin, or decreases GIP without affecting insulin, GLP-1, or ghrelin." (PMID 36832775, 2023).
Anxiety (107 papers, 2010 to 2026). Intense feelings of nervousness, tension, or panic often arise in response to interpersonal stresses. "For example, anxiety is associated with increased cholecystokinin (CCK) release, an opioid antagonist, and reduced opioid receptor function." (PMID 41303122, 2025). "Chemogenetic studies extend this causal link: silencing parvalbumin- or CCK-positive interneurons in the basolateral amygdala precipitates depressive- and anxiety-like behaviours, whereas their activation rescues mood, underscoring circuit specificity." (PMID 41373485, 2025). "CCK has been implicated in anxiety and depression in pre‐clinical models, and administration of CCK‐4 is associated with anxiety and panic attacks in humans." (PMID 40222815, 2025). "CCK has also been implicated in anxiety (Harro, Vasar, and Bradwejn 1993) and anxious temperament, and CCKB receptor regulation is altered in anxious states in animals and humans (Harro, Lang, and Vasar 1990, Harro, Marcusson, and Oreland 1992)." (PMID 39607287, 2024). "Anticipatory anxiety activates cholecystokinin which facilitates pain transmission and is implicated in the nocebo response." (PMID 37020314, 2023). "The cholecystokinin gene (CCK) has been studied in relation to anxiety and cognition and more recently has been associated with body mass index, similar to other neuropeptides that have been found to regulate eating behaviour and energy homeostasis." (PMID 38254919, 2023). "As for the hormone encoders, CCK is involved in several activities such as satiety regulation, enzyme secretion, gut motility, and anxiety, whereas IGF1R is an important regulator of intestinal cell growth and differentiation." (PMID 34873196, 2021). "Brain CCK has been increasingly implicated as a key regulator in diverse aspects of behavior, including feeding, satiety, memory, nociception, and anxiety." (PMID 34766905, 2021). "Previous study implicated that the cholecystokinin system is closely linked with various human psychiatric disorders, such as bipolar disorder and panic attacks." (PMID 32314736, 2020). "Remarkably, changes in methylation nearby and expression of the gene encoding cholecystokinin, which were inversely correlated to each other, were associated with variations in anxiety-related phenotypes." (PMID 31133792, 2019). "Studies have shown that CCK gene variants may be associated with different anxiety phenotypes, and CCKAR may play a role in the development of panic comorbid with bipolar disorder." (PMID 40243462, 2025). "CCK activity has been also linked to social stress-induced anxiety and depression." (PMID 36004833, 2022). "CCK is an enteroendocrine hormone associated with hunger and anxiety." (PMID 34149609, 2021). "CCK is a neurotransmitter peptide in the central nervous system and is associated with anxiety." (PMID 34506507, 2021). "CCK is intimately involved in diverse normal behaviours such as learning and memory, feeding, satiety, and detection of painful stimuli; it is also strongly linked to several central nervous system disorders, including anxiety and panic attacks." (PMID 34966625, 2021). "Although both inhibitory and excitatory CCK positive neurons are associated with emotional behaviors such as anxiety and depression, inhibitory CCK positive neurons might be specifically altered and associated with anxiety-like behavior in OLETF rats." (PMID 32938363, 2020). "Indeed, negative expectations associated with the nocebo effect have been shown to induce anxiety, thereby increasing cholecystokinin (CCK) release." (PMID 33467255, 2020). "Some evidence points to anxiety as an important factor in this context, in line with the notion that anxiety-triggered cholecystokinin activation might cause nocebo hyperalgesia." (PMID 29321752, 2017). "Therefore, large and small types of CCK and PV positive neurons in the amygdala might be differentially altered and associated with anxiety-like behavior in OLETF rats." (PMID 32938363, 2020).
Anxiety (continued). "Moreover, CCK is particularly associated to anxiety- and panic-related behaviors across species." (PMID 31133792, 2019). "Notably, CCK release from CCK-GABA neurons may be linked to the subtle increase in anxiety-like behaviors observed in our study and other models." (PMID 30834305, 2019). "Within the BLA, specific interneuron subtypes, such as parvalbumin (PV+), somatostatin (SOM+), and cholecystokinin (CCK+) interneurons, modulate amygdala output and anxiety-like behaviors, and facilitation of endocannabinoid signaling, respectively." (PMID 40635883, 2025). "The most important neuropeptides that play a role in modulating stress and anxiety-related behaviours are cholecystokinin, oxytocin, and ghrelin." (PMID 40559398, 2025). "There are also unresolved issues regarding the involvement of brain CCK in the pathogenesis of anxiety and panic disorders, including therapeutic trials using CCK2 receptor antagonists." (PMID 40243462, 2025). "Administration of the tetrapeptide cholecystokinin (CCK-4) has been shown to induce panic attacks in both patients with panic disorder and healthy volunteers, suggesting a direct effect of CCK on the mechanisms of anxiety." (PMID 40243462, 2025). "Cholecystokinin B receptor (CCKBR) and cholecystokinin (CCK) in sensory ganglia, spinal cord, and supraspinal neurons mediate nociception, morphine insensitivity, and anxiety in numerous rodent pain models." (PMID 38999998, 2024). "Recent experiments suggest that gut dysbiosis in alcohol-dependent patients can promote anxiety-like and depression-like behaviors in animal models, potentially facilitating alcohol dependence by influencing cholecystokinin (CCK) and related receptors." (PMID 39845646, 2024). "Overall, it appears that there is an interaction and a link between cholecystokinin (CCK), pain, and anxiety." (PMID 39021437, 2024). "More importantly, the CCK-BR scFv was able to stem the increase in anxiety and depression characteristic of the chronic trigeminal neuropathic pain model." (PMID 37446213, 2023). "Microbiota-mediated enteroendocrine and enterochromaffin cells in the intestinal epithelium can release multiple gut hormones, including 5-HT, PYY, GLP-1, CCK, and ghrelin, which regulate multiple brain disorders, such as anxiety and depression." (PMID 38057297, 2023). "Some studies investigated the brain response to cholecystokinin-tetrapeptide (CCK-4), a compound that induces panic attacks in susceptible individuals, in patients with OCD and healthy control groups." (PMID 38046120, 2023). "CCK-BR scFvs given in week 3 diminished the anxiety-like behaviors that develop after 4–6 weeks of persistent hypersensitivity in FRICT-ION (or in any chronic model)." (PMID 37446213, 2023). "Untreated mice with FRICT-ION, mice treated with low dose 0.04 mg/kg CCK-BR scFv, and mice treated with the control Zika scFv all developed both anxiety and depression." (PMID 37446213, 2023). "Validation of the efficacy of the lead CCK-BR scFv antibodies for the reduction of hypersensitivity, anxiety-, and depression-like behaviors was investigated in a chronic trigeminal neuropathic pain model in mice persisting 3–4 months." (PMID 37446213, 2023). "Vagal deafferentation by cholecystokinin-saporin (CCK-SAP) reduces anxiety-like behaviors in DSS-induced colitis mice." (PMID 37200091, 2023). "In both paradigms, however, changes in locomotor activity mediate the effect of CCK-SAP on anxiety surrogate variables." (PMID 35965105, 2022). "CCK is also found throughout the CNS, and high CCK levels have been shown to promote anxiety and panic disorders within humans and rodents." (PMID 35356729, 2022). "CCK+ neurons are involved in relevant behavioral functions, such as memory, cognition, anxiety, and reward, by regulating their cognitive components." (PMID 35571372, 2022). "Other-CCK mediated regulatory functions in the brain have been discovered: in sleep, nociception, memory and learning processes, panic and anxiety." (PMID 35286508, 2022).
Anxiety (continued). "In summary, CCK is a promising target in the treatment of anxiety and depression, though a more robust body of clinical trials has to be at hand to implement this approach to the evidence-based complex management of these two conditions." (PMID 36004833, 2022). "Surprisingly, the endogenous CCK reactivation of the CCK-B receptor restored the benchmark anxiety levels." (PMID 36004833, 2022). "The role of CCK-ergic neurotransmission in the pathogenesis of anxiety and depression was also evidenced by the infusion of CCK-B receptor agonists, producing similar effects." (PMID 36004833, 2022). "The authors found an inverse correlation between CSF levels of CCK and proneness to anxiety, depression, and suicidal behavior." (PMID 36004833, 2022). "Injecting a high dose of the CCK fragment CCK-4 into humans induces panic attacks, and it has also been found to induce anticipatory anxiety even in healthy individuals." (PMID 35893544, 2022). "Research has revealed a strong relationship of the nocebo response with the anxiety triggered by the cholecystokinin (CCK)." (PMID 34497495, 2021). "A role for CCK cells in depression and anxiety was suggested by recent studies which applied chemogenetic manipulation of hippocampal CCK cells." (PMID 33742167, 2021). "Subsequently, the review discusses three unsettled questions about the involvement of cerebral CCK in the pathogenesis of anxiety and panic disorder, including therapeutic attempts with CCK2-receptor antagonists." (PMID 34577128, 2021). "While endocannabinoid and some serotonergic receptors mediate inhibition of CCK cells that lead to antidepressive-like behaviors, the cholinergic receptors activate CCK cells, which results in modulation in both anxiety and depressive-like behaviors." (PMID 33723417, 2021). "Behavioral studies have documented the dominant role of CCK in nocebo hyperalgesia via anticipatory anxiety mechanisms." (PMID 34497495, 2021). "Numerous studies have investigated the role of CCK in moderating anxiety and the stress response in humans." (PMID 33920547, 2021). "The most important neuropeptides that play a role in modulating stress and anxiety-related behavior are cholecystokinin (CCK), oxytocin (OXT), and ghrelin." (PMID 33920547, 2021). "Systemic chemogenetic activation of CCK-positive inhibitory neurons reportedly increased anxiety-like behavior in the elevated plus maze test." (PMID 34506507, 2021). "We recently reported that 20-week-old OLETF rats exhibited increased anxiety-like behavior in the open-field test, area reduction, and increased cholecystokinin (CCK)-positive neurons in the corticolimbic system." (PMID 34506507, 2021). "CCK and its receptors are intrinsically involved in fear-related mental disorders including anxiety, depression, and post-traumatic stress disorder (PTSD)." (PMID 34779397, 2021). "On the contrary, in a companion paper, we reported notable depressive- and anxiety-like behaviors following the upregulation of Neurensin-2 in DG CCK cells, and here we confirmed that these mice retain normal behavioral response to the SSRI." (PMID 33723417, 2021). "In the brain, where the prevailing form of CCK is the sulfated octapeptide, CCK-8, it regulates satiety, anxiety, but also cognition, reward, learning and memory." (PMID 34948415, 2021). "To examine the additional mechanisms underlying anxiety-like phenotypes in OLETF rats, we measured the densities of CCK- and PV-positive neurons in the corticolimbic system." (PMID 34506507, 2021). "Global chemogenetic activation of CCK positive inhibitory neurons increases anxiety-like behavior in the elevated plus maze test." (PMID 32938363, 2020). "There are also several gut hormones, including NPY, GLP-1, cholecystokinin (CCK), and ghrelin, that are known to play important roles in mood disorders such as anxiety and depression." (PMID 33287416, 2020).